LGALS3 (galectin 3)
Diseases named in the same sentence as LGALS3 in open-access papers (continued):
Sharing a sentence is not in itself a finding about the gene and the disease.
chondrosarcoma (2 papers, 2021 to 2023). A malignant cartilaginous matrix-producing mesenchymal neoplasm arising from the bone and soft tissue. "Immunohistochemical analysis of human mesenchymal chondrosarcoma cases also showed positive expressions of CK18 and GAL3, gene products of KRT18 and LGALS3, respectively." (PMID 37212282, 2023). "Expression of Krt8, Krt18, and Lgals3, which are notochord markers, was observed in cluster 6, suggesting that dysregulated differentiation might also occur in mesenchymal chondrosarcoma, unlike normal chondrocytic differentiation." (PMID 37212282, 2023).
clear cell renal cell carcinoma (2 papers, 2011 to 2023). "Here, we studied the expression as well as the distribution of galectin-3 in clear cell renal cell carcinoma (CCRCC) from 39 patients." (PMID 21958686, 2011). "Our data indicate that changes in the cellular level of galectin-3 correlate with the development of clear cell renal cell carcinoma, which is in line with previously published data on this specific type of tumor." (PMID 21958686, 2011). "To study a putative correlation between the extent of galectin-3 and the development of clear cell renal cell carcinoma, we monitored the quantity and distribution of this lectin in tissue samples from 39 patients." (PMID 21958686, 2011).
Cluster headache (2 papers, 2024 to 2025). A type of headache characterized by repeated attacks of unilateral pain lasting 15 to 180 minutes and associated with local autonomic signs. "In addition, MERTK ligand galectin-3 was found at increased concentration in the serum of study participants with cluster headache, whereas the levels of MERTK ligands growth arrest specific 6 and protein S unaffected." (PMID 38783191, 2024).
coronary artery calcification (2 papers, 2022 to 2025). Calcification of the coronary artery, used as a measure of coronary atherosclerosis, a risk factor for myocardial infarction. "Receiver operating characteristic (ROC) curve was used to analyze the prognostic value of galectin-3 or BaPWV for coronary artery calcification (CAC)." (PMID 35685493, 2022).
diffuse Lewy body disease (2 papers, 2017 to 2021). "To determine if endocytosis-mediated seeding and endo-lysosome rupture are involved in the progression of αS pathology in vivo, we investigated Galectin-3 co-localization with αS pathology in Lewy body disease." (PMID 28794446, 2017).
facioscapulohumeral muscular dystrophy (2 papers, 2023 to 2025). An autosomal dominant disorder affecting the skeletal muscles of the face, scapula, and upper arm. "A very recent study showed the overexpression of Lgals3 in macrophages extracted from skeletal muscles of mouse models of valosin-containing protein-associated inclusion body myopathy, facioscapulohumeral muscular dystrophy, and Duchenne muscular dystrophy." (PMID 40229243, 2025).
fungal keratitis (2 papers, 2022). "To explore the immune mechanisms underlying galectin-3 in the regulation of fungal keratitis, we first analyzed neutrophils, which play a significant role in the innate immunity of keratitis, at different stages of the disease." (PMID 35845133, 2022). "The expression of the galectin-3 was detected by quantitative real-time Polymerase Chain Reaction (qPCR), enzyme-linked immunosorbent assay (ELISA), and immunofluorescence in the corneal tissue of the fungal keratitis mouse model." (PMID 35437453, 2022). "Our study is aimed at clarifying the role of galectin-3 in the fungal keratitis mouse model in vivo, thereby providing a new biomarker of antifungal therapy." (PMID 35437453, 2022). "The mouse model of fungal keratitis was established to further verify the high expression of galectin-3 in fungal keratitis and its potential regulatory mechanism." (PMID 35437453, 2022). "It was implied that the expression of galectin-3 has a positive effect on neutrophil recruitment in fungal keratitis." (PMID 35437453, 2022). "The deterioration of fungal keratitis and increased fungal load in corneal lesions of galectin-3 knockout mice proved the regulatory role of galectin-3 in fungal keratitis." (PMID 35437453, 2022). "Next, we analyzed the potential correlation between the expression of galectin-3 and neutrophil activation in peripheral blood samples of patients with fungal keratitis." (PMID 35845133, 2022). "Our results demonstrate that galectin-3, an essential immunological marker, participated in the immune responses and increased obviously in different stages of fungal keratitis." (PMID 35845133, 2022). "The co-location expression results of galectin-3 and the typical markers of neutrophils (CD11b), and HCECs (CK12) reveal the co-resistance of galectin-3 and neutrophils in fungal keratitis lesions." (PMID 35845133, 2022). "To illustrate the effect of galectin-3 on immune cells in the mouse model of fungal keratitis, we first examined neutrophils' levels under different conditions." (PMID 35437453, 2022). "This study is designed and aimed at providing evidence to support the vital role of galectin-3 in fungal keratitis immune disorders, pointing out the key disease marker." (PMID 35437453, 2022). "To further investigate the role of galectin-3 in fungal keratitis, we determined the expression of galectin-3 in cell model in vitro of fungal keratitis and in corneal tissues collected from patients with fungal keratitis." (PMID 35845133, 2022). "Next, we analyzed galectin-3 expression in corneal tissues collected from corneal transplantation surgery of patients with fungal keratitis." (PMID 35845133, 2022). "To further study the regulation of galectin-3 in fungal keratitis, we established the mouse model of the wild type mice and galectin-3 knockout (galectin-3−/−) mice to evaluate the effect on the course of the disease." (PMID 35437453, 2022). "In conclusion, galectin-3 is going to be an essential target to modulate neutrophil recruitment and its related antifungal immune response in fungal keratitis." (PMID 35437453, 2022). "Conclusively, our results demonstrated that galectin-3 could be a significant and promising disease marker in fungal keratitis, and the galectin-3 modulation correlated with neutrophils in fungal keratitis at the early and late stages." (PMID 35845133, 2022). "In other words, galectin-3 might be a promising target for fungal keratitis therapeutic strategy in the future, which will shed some light on fungal keratitis patients, who are first to care." (PMID 35845133, 2022). "It is noteworthy that the expression level of galectin-3 was the highest in both early and late stages among detected cytokines, suggesting that it may play an important role in fungal keratitis." (PMID 35845133, 2022). "Therefore, targeting galectin-3 in anti-infection immune response would be a potential therapeutic alternative for fungal keratitis." (PMID 35437453, 2022).
fungal keratitis (continued). "In conclusion, galectin-3 could be a key disease marker implying a beneficial immune response in the pathogenesis of fungal keratitis, which might be a target of therapeutic strategy in the future." (PMID 35845133, 2022). "Meanwhile, colocalization and a positive correlation between galectin-3 and neutrophils were observed, suggesting that galectin-3 may play a crucial role in the recruitment of neutrophils and immune regulation of fungal keratitis." (PMID 35845133, 2022). "The results above suggested that galectin-3 may prevent and/or inhibit the fungal keratitis progression and positively regulate the fungal clearance of inflammatory cells." (PMID 35437453, 2022). "Our finding of a significant increase of galectin-3 in tear samples of patients with fungal keratitis suggests that galectin-3 might be an indicator of the initiation of immune reactions in human fungal keratitis." (PMID 35845133, 2022). "Furthermore, decreased activity of neutrophils, which are responsible for fungus control and antigen presentation, also explains the faster corneal perforation in the galectin-3−/− mice of fungal keratitis." (PMID 35437453, 2022). "Elevated expression of galectin-3 and its localization to the corneal epithelium and stroma suggested that galectin-3 may play an important immune regulatory function by recruiting and activating neutrophils in fungal keratitis." (PMID 35845133, 2022). "It suggested that galectin-3 may play an important role in fungal keratitis." (PMID 35437453, 2022). "Moreover, neutrophils were intensely activated in the course of fungal keratitis, and the positive correlation and colocation of galectin-3 and neutrophils suggested that galectin-3 may play an immune regulatory role by recruiting neutrophils in the early and late stages of fungal keratitis." (PMID 35845133, 2022). "It has not been reported that galectin-3 regulates neutrophil functions, including recruitment, killing, and response to immune-modulatory cytokines in the fungal keratitis model in vivo." (PMID 35845133, 2022). "The role of galectin-3 in fungal keratitis has not been studied previously." (PMID 35845133, 2022).
gastroenteritis (2 papers, 2022 to 2025). An inflammatory disorder that affects the upper and lower gastrointestinal tract. "In the case of Salmonella, a Gram-negative bacterium associated with food poisoning and gastroenteritis, rupture of the PcV induces the recruitment of LGALS3 (galectin 3) LGALS8 and LGALS9, with LGALS8 playing a unique role as a danger receptor that inhibits bacterial proliferation." (PMID 40910070, 2025).
geographic atrophy (2 papers, 2022 to 2025). "That study identified a specific subset of TREM2+ and galectin‐3 (GAL3+) microglia enriched in the macular region of patients with AMD, particularly in the subretinal space and in areas of geographic atrophy." (PMID 40716081, 2025). "Galectin-3 expression was mainly localized to activated microglia in the degenerating outer nuclear layer (ONL) and subretinal space in AMD patients with geographic atrophy (GA)." (PMID 36115971, 2022).
hematoma (2 papers, 2019 to 2023). A hematoma is a collection of blood from a vascular structure into an extravascular space. "Besides, Galectin-3 expressing microglia or macrophages exhibited phagocytic phenotype implicating its unexplored role in microglial or macrophage mediated phagocytosis, which plays a key role in hematoma resolution and subsequent brain recovery after ICH." (PMID 31156388, 2019).
hemorrhagic stroke (2 papers, 2021). A stroke caused by a bleed on the brain. "Plasma galectin-3 levels increase in cerebral hemorrhage, which aggravates neuroinflammation and is closely related to poor prognosis, and may become a prognostic biomarker of hemorrhagic stroke." (PMID 34900086, 2021).
herpes zoster (2 papers, 2012 to 2023). A common dermal and neurologic disorder caused by reactivation of the varicella-zoster virus that has remained dormant within dorsal root ganglia, often for decades, after the patient's initial exposure to the virus in the form of varicella (chickenpox). "Nevertheless, any such effect on neuroinflammation may be conditionally dependent, as galectin-3 depletion reduced inflammation and the severity of experimental autoimmune encephalitis, and reduced pain due to macrophage invasion in herpes zoster induced allodynia." (PMID 23139902, 2012).
hyperprolactinaemia (2 papers, 2023 to 2024). "Our study found that hyperprolactinemia, as indicated by bromocriptine use, was significantly associated with galectin-3 levels." (PMID 39958874, 2024). "In the context of emerging research on PCOS and galectin-3 levels, our study presents a unique insight into the influence of metformin dosage and hyperprolactinemia." (PMID 39958874, 2024). "The role of hyperprolactinemia as a comorbidity in our real-life cohort offers important insights into the modulation of galectin-3 levels." (PMID 39958874, 2024). "Further research is warranted to disentangle these variables and better understand how hyperprolactinemia influences galectin-3 modulation in PCOS." (PMID 39958874, 2024). "This study aims to address these gaps by investigating how both metformin dosage and hyperprolactinemia influence galectin-3 levels, potentially offering new insights into personalized treatment protocols." (PMID 39958874, 2024). "This real-life approach allowed for the inclusion of a broad spectrum of clinical scenarios, providing a realistic assessment of the impact of metformin and hyperprolactinemia on galectin-3 levels in women with PCOS." (PMID 39958874, 2024). "Moreover, we report that hyperprolactinemia significantly elevates galectin-3 levels, adding another layer to the multifaceted relationship between metabolic, hormonal, and therapeutic factors in PCOS." (PMID 39958874, 2024). "Our study provides important insights into the modulation of galectin-3 levels by metformin dosage and hyperprolactinemia in women with PCOS, highlighting the relevance of patient-specific treatment strategies for addressing the complex metabolic and hormonal challenges of this condition." (PMID 39958874, 2024). "Furthermore, an in-depth exploration of metformin’s pharmacodynamics, particularly its interaction with galectin-3 in the presence of hyperprolactinemia, is critical." (PMID 39958874, 2024). "The real-life approach of our study enhances the relevance of the results and provides a better understanding of how different metformin dosages and the presence of hyperprolactinemia influence galectin-3 levels, potentially leading to more personalized therapeutic strategies." (PMID 39958874, 2024). "Since galectin-3 levels were not directly correlated with metformin concentration, this may indicate a nuanced interaction between dosage, administration patterns, and the broader hormonal environment in hyperprolactinemia." (PMID 39958874, 2024).
inflammatory skin disease (2 papers, 2020 to 2021). Inflammatory skin disorders covers a broad category that includes many conditions ranging in severity, from mild itching to grave medical health complications These disorders are common in people of all ages and races. "There has been no previous report evaluating galectin-3 in dogs with endocrine or inflammatory skin disease, but it is known that galectin-3 is related to specific endocrine or skin disease in humans." (PMID 34722704, 2021). "Research on evaluating galectin-3 in dogs with AD or other inflammatory skin diseases is lacking, but the expression of galectin-3 was reported in dogs with squamous cell carcinoma of the skin." (PMID 34722704, 2021).
Kaposi's sarcoma (2 papers, 2022 to 2023). A malignant neoplasm characterized by a vascular proliferation which usually contains blunt endothelial cells. "Galectin-3 has been implicated in KSHV infection and Kaposi’s sarcoma pathogenesis." (PMID 37298569, 2023).
keloid (2 papers, 2022 to 2026). An irregularly shaped, elevated mark on the skin caused by deposits of excessive amounts of collagen during wound healing. "Additionally, studies have shown that galectin-3 (GAL-3) in human keloid tissue is significantly positively correlated with the gene expression of type I collagen, indicating that GAL-3 may play an important role in the pathological formation of keloids." (PMID 41596210, 2026).
kidney cancer (2 papers, 2016 to 2025). Primary or metastatic malignant neoplasm involving the kidney. "Interestingly, SET expression is deregulated in more than 10 % of kidney cancer samples, a cancer type where we have previously demonstrated increased nuclear translocation of galectin-3." (PMID 27435226, 2016).
laryngeal carcinoma (2 papers, 2014 to 2017). Carcinoma that arises from the laryngeal epithelium. "In another study regarding laryngeal cancer, Galectin-3 labeled digitized microscopy images of patients with in situ laryngeal carcinoma, laryngeal invasive squamous cell carcinoma, and cervical lymph nodes were analyzed by a commercial software." (PMID 25763351, 2014). "High Galectin-3 expression was related to the invasiveness and aggressiveness of laryngeal carcinomas." (PMID 25763351, 2014).
lipid metabolism disorders (2 papers, 2020 to 2021). "What is known about galectin 3 is that it is responsible for initiation of inflammatory macrophage infiltration within the adipose tissue; this is in turn correlated with both carbohydrate and lipid metabolism disorders." (PMID 32859099, 2020).
Lymphatic Metastasis (2 papers, 2011 to 2022). Transfer of a neoplasm from its primary site to lymph nodes or to distant parts of the body by way of the lymphatic system. "Furthermore, although Kaplan-Meier analyses denoted non-significant correlation between galectin-3 overall and disease-free survival rates, which was similar to the work reported previously, however, lower galectin-3 expression has been significantly associated with lymphatic metastasis." (PMID 36713574, 2022).
mental disorder (2 papers, 2022 to 2025). A disease that has its basis in the disruption of mental process. "Galectin-3 has been investigated in animal and human studies of different mental disorders, but mainly as an alarmin, a biomarker of a particular disease stage." (PMID 35875353, 2022).
migraine (2 papers, 2021 to 2024). "Interestingly, galectin-3 deficiency has similar neuroprotective effects in migraine, acute spinal cord injury (SCI), and traumatic brain injury (TBI)." (PMID 34900086, 2021). "Further, the MERTK ligand galectin-3 has been found to be elevated in serum of migraine patients." (PMID 38783191, 2024).
mycosis fungoides (2 papers, 2021 to 2023). Classical mycosis fungoides is the most common type of mycosis fungoides (MF), a form of cutaneous T-cell lymphoma, and is characterized by slow progression from patches to more infiltrated plaques and eventually to tumors. "On the other hand, galectin-3 is positive in primary cutaneous ALCL but has a lower expression in mycosis fungoides with large cell transformation." (PMID 37627126, 2023).
nasal polyps (2 papers, 2006 to 2014). "The regulation of polypoid growth is biochemically determinated by various factors, like galectin-3, known of anti-apoptotic activity, which expression is markedly higher in nasal polyps than in nasal turbinate." (PMID 16551346, 2006).
nematode infection (2 papers, 2014 to 2025). "While the expression of LGALS3 in ovine whole blood can be upregulated by garlic supplementation, its involvement in GI nematode infections in small ruminants has not been reported before." (PMID 40811742, 2025).
neovascular age-related macular degeneration (2 papers, 2024 to 2025). "However, the involvement of Lgals3/galectin-3 in eyes with neovascular age-related macular degeneration (nAMD) remains unknown." (PMID 39595213, 2024).
neuroendocrine tumor (2 papers, 2015 to 2020). "The strong galectin-3 expression also differentiates it from the galectin-3-negative neuroendocrine tumors." (PMID 31209654, 2020). "Such a marker could be the galectin-3, which is useful to distinguish SPN from neuroendocrine tumors, but it is also interesting that its low immunohistochemical expression is associated with metastatic spreading." (PMID 31209654, 2020). "Similarly, β-catenin, glypican-3 or galectin-3 are positive in SPN, but the neuroendocrine tumors are negative." (PMID 31209654, 2020).
osteoporosis (2 papers, 2017 to 2026). A condition of reduced bone mass, with decreased cortical thickness and a decrease in the number and size of the trabeculae of cancellous bone (but normal chemical composition), resulting in increased fracture incidence. "Therefore, it is tempting to speculate that the age-dependent reduction of galectin-3 EVs content might contribute to the reduction of bone formation, development of osteoporosis, and increased facture risk in the elderly." (PMID 29160796, 2017). "These analyses could provide valuable information possibly helping in identifying galectin-3 as potential therapeutic target in some bone pathologies, primarily senile osteoporosis." (PMID 29160796, 2017).